EGFR (epidermal growth factor receptor)
Diseases named in the same sentence as EGFR in open-access papers (continued):
Sharing a sentence is not in itself a finding about the gene and the disease.
glioblastoma (continued). "Interestingly, it was revealed that the signaling of EGF through the EGF receptor (EGFR) is implicated in the proliferative mechanism of glioblastomas." (PMID 34638718, 2021). "In IDH-wildtype glioblastomas (n = 2,072), we identified distinct tumor clusters based on immune cell proportion and demonstrated an association with oncogenic alterations such as EGFR amplification and CDKN2A/B homozygous deletion." (PMID 34496929, 2021). "Indeed, EGFR gene is frequently mutated, amplified or overexpressed in various kinds of tumours including Glioblastoma multiforme (GBM), the most aggressive brain tumour in adults." (PMID 32823532, 2020). "Primary glioblastoma primarily occurs in older patients (mean age, 62–64 years) and typically shows epidermal growth factor receptor (EGFR) overexpression, PTEN mutations, cyclin-dependent kinase inhibitor (CDKN2A) (p16) deletion, and, sometimes, mouse double minute 2 homolog (MDM2) amplification." (PMID 32987955, 2020). "It is well established that amplification and mutations of epidermal growth factor receptor (EGFR) are the most frequent genetic event in glioblastoma, which promotes tumor growth and survival through uncontrolled activation of signaling networks and metabolic reprogramming." (PMID 32051553, 2020). "Thus, in glioblastoma patients, the use of CSF-derived EVs yield high specificity for the detection of tumor-associated EGFR amplifications." (PMID 33575258, 2020). "In addition, 24% of glioblastoma samples have point mutations in the extracellular region of EGFR which keep EGFR in active conformation." (PMID 31968687, 2020). "β-catenin can be activated not only by Wnt ligands but also by receptor tyrosine kinases, such as epidermal growth factor receptor (EGFR), whose mutation or overexpression of EGFR gene occurs in many types of human cancer, including more than 50% of glioblastoma (GBM)." (PMID 32195176, 2020). "Another commonly noted feature of glioblastoma is the mutation and amplification of the EGFR gene." (PMID 33117083, 2020). "We will examine how circulating EVs positive for EGFR may be exploited as diagnostic, prognostic or therapeutic markers in cancers including breast, lung, glioblastoma, ovarian and prostate." (PMID 33143170, 2020). "Mutations in EGFR have been widely recognized to be involved in the pathogenesis of glioblastomas." (PMID 32290213, 2020). "A novel lentiviral vector of one miRNA cluster and epidermal growth factor receptor (EGFR)-variant III was introduced into CAR T cells to enhance the durability of its therapeutic response in glioblastoma, which effectively improved the efficacy of adoptive T cells." (PMID 32792861, 2020). "As over-expression of EGFR is associated with the growth of the glioblastoma cells; we therefore sought to test whether up-regulation of miRNA-7 could inhibit the cell growth." (PMID 32592373, 2020). "In conclusion, our results highlight that the dPCR assay using LNA-hydrolysis probes allowed the simultaneous detection of the EGFR amplification and EGFRvIII variant and may be used routinely in patients treated for glioblastoma." (PMID 32303258, 2020). "In another report, Gomez GG found the EGFR mutation-induced miR-9 suppression could elevate glioblastoma tumorigenicity by activating FOXP1." (PMID 30795814, 2019). "Artificial antisense miRNAs could be produced and used to block their targeted oncomiRs associated with EGFR to inhibit the progression of glioblastoma." (PMID 31013819, 2019).
glioblastoma (continued). "Concomitant chromosome 7p gain combined with chromosome 10q loss is the most frequent genetic alteration in glioblastoma, with almost half showing both alterations; a large fraction of EGFR amplification occurs on a background of chromosome 7 polysomy and chromosome 10 monosomy." (PMID 30967140, 2019). "The unexpected finding of lower expression linked to the EGFR variant could indicate different mechanisms in the initiation phase towards glioma development, compared with the fully developed glioblastoma stage." (PMID 31842352, 2019). "D2C7 is a novel monoclonal antibody (mAb) that reacts with both the wild-type epidermal growth factor receptor (EGFRwt) and the mutant EGFR variant III (EGFRvIII) (both of which are major glioblastoma driver oncogenes) overexpressed on the surface of cancer cells." (PMID 31142380, 2019). "Besides EGFR overexpression and mutation, epigenetic mechanisms are increasingly known to be key contributing factors in the progression and development of glioblastoma." (PMID 31013819, 2019). "Two harbored glioblastoma-like mutations, including EGFR, PTEN, and NF1." (PMID 31788444, 2019). "Furthermore, in Glioblastoma Multiforme, 1p/19q co-deletion, a widely used prognostic biomarker for brain tumors, and epidermal growth factor receptor (EGFR) mutations, have been correlated with a wide array of MRI features." (PMID 31590671, 2019). "For example, activation of SREBP1 and enhanced expression of its target genes have been observed in human glioblastoma multiforme carrying activating EGFR mutations and inhibition of lipid synthesis blocks the growth of xenograft tumors derived from glioblastoma cells expressing mutant EGFR15." (PMID 29449559, 2018). "We investigated whether Sym004 induces removal of EGFRvIII and if this removal translates into tumor growth inhibition in hard-to-treat glioblastomas (GBMs) harboring the mutated, constitutively active EGFR variant III (EGFRvIII)." (PMID 29564747, 2018). "A recent study provided evidence that EGFRvIII associates with EGFR and this association is essential for its oncogenic activity: in EGFRvIII+ glioblastoma cells the EGFRvIII+ cells co-express the WT-EGFR, while the cells expressing only the mutant receptor, without the WT receptor are very rare." (PMID 30279357, 2018). "EGFR is often overexpressed or mutated in diverse cancer types and especially in glioblastoma." (PMID 29377763, 2018). "Glioblastomas (GBMs) are high‐grade brain tumors, differentially driven by alterations (amplification, deletion or missense mutations) in the epidermal growth factor receptor (EGFR), that carry a poor prognosis of just 12–15 months following standard therapy." (PMID 29313975, 2018). "EGFR overexpression, occurring in 30–70% of primary glioblastomas is the most frequent mutation." (PMID 28620312, 2017). "EGFRvIII could be considered a safe tumor target because it is a mutated form of EGFR expressed on glioblastoma multiforme (GBM) tumors." (PMID 28434147, 2017). "In addition, EVs were also shown to transfer the oncogenic form of EGFR, EGFRvIII, between glioblastoma cells as well as to ECs, causing phenotypic modulation of recipient cells." (PMID 28730141, 2017). "In addition, the EGFR variant EGFRvIII arises from the genomic deletion of exons 2–7, and occurs in approximately 20% of glioblastomas." (PMID 28513565, 2017).
glioblastoma (continued). "The most common EGFR alteration associated with glioblastoma is amplification." (PMID 28785587, 2017). "An aptamer capable of targeting EGFR and the mutant variant EGFRvIII would serve to be an ideal candidate for use in glioblastoma therapy, as their overexpression and mutation are prevalent in the majority of glioblastoma tumours." (PMID 29189740, 2017). "Interestingly, the EVs derived from CSFs contain RNA signatures reflective of the underlying molecular genetic status of glioblastoma in terms of wt EGFR expression and EGFRvIII status." (PMID 28730141, 2017). "Current evidence suggests that EGFR amplification is a hallmark of glioblastoma (GBM)." (PMID 28938685, 2017). "Interestingly, proteomic analysis of a set of 27 surgical glioblastoma samples revealed that activation of Notch signaling is highly correlated with EGFR activation, a hallmark of the classical subtype of GBM tumors." (PMID 27043632, 2016). "Among them, Rindopepimut, the EGFR-derived 14-mer peptide vaccine consisting of the mutation site of EGFRvIII, has been demonstrated as a safe and potentially effective drug for the treatment of glioblastoma multiforme (GBM) in phase II clinical trials." (PMID 27659529, 2016). "In our study, the long lag time (almost 15 years) between sample donation and glioblastoma diagnosis indicates that increased serum EGFR and ErbB2 are likely to be associated with an etiological factor more than with the effects of undiagnosed disease (i.e., reverse causation)." (PMID 26906551, 2016). "EGFR is mutated and amplified in up to 70 % of primary glioblastomas." (PMID 26906551, 2016). "In addition, PLK1 inhibition has been shown to significantly augment the anti-tumor effect of EGFR inhibitors in EGFR inhibition–resistant glioblastoma cell lines harboring EGFRvIII mutations." (PMID 27384992, 2016). "EGFR point mutations have also been identified in glioblastoma." (PMID 26858939, 2016). "EGFR amplification was associated with worse outcomes in glioblastoma patients." (PMID 27437777, 2016). "Glioblastoma patients harbor a constitutively active oncogenic variant of epidermal growth factor receptor (EGFR-vIII) that is formed by the in-frame deletion of exons 2 to 7 in the EGFR gene and found on extrachromosomal DNA." (PMID 26755558, 2016). "In combination with loss of nuclear ATRX expression, IDH1, 1p/19q and TERT promoter mutations define the most frequent type of infiltrative astrocytoma, while mutations in the EGFR gene (seen in 35 % of all cases of glioblastoma) are associated with primary glioblastoma." (PMID 26839018, 2016). "Similarly, glioblastoma-associated EGFR-vIII, which lacks the normal EGFR's ability to undergo ligand-triggered lysosomal traffic, is HSP90-associated." (PMID 26859680, 2016). "Between 40 and 50 % of glioblastoma multiforme (GBM) cases carry alterations of the EGFR, and approximately half of these co-express the mutated variant EGFRvIII, which has a deletion of exons 2–7 that generates a constitutively active receptor, even in the absence of ligand binding." (PMID 24352766, 2014). "Moreover, loss of Anxa7 tumor suppressor expression with gain in epidermal growth factor receptor protein induced survival signaling pathway and reported earlier, demonstrated to be a high risk factor in evaluating the survival of glioblastoma patient." (PMID 24550987, 2014). "Interestingly, activation of LXR using GW3965 has been shown to sensitize glioblastoma cells expressing EGFR splice variant (EGFRvIII) to apoptosis in in vivo models of glioblastoma." (PMID 25184494, 2014).
glioblastoma (continued). "The epidermal growth factor receptor (EGFR)/ErbB1 gene amplification is one of the most frequent alterations, occurring in 30–40% of malignant glioblastoma and it has been associated with tumor invasiveness, angiogenesis, poor survival, and resistance to radiation therapy." (PMID 25261371, 2014). "Primary glioblastomas typically occur in patients older than 50 years of age and are characterized by epidermal growth factor receptor (EGFR) amplification and mutations, loss of heterozygosity of chromosome 10q and other abnormalities as reviewed in Wen and Kesari (2008)." (PMID 25228849, 2014). "In the present study, the expressions and mutation of EGFR were tested with [125I] PYK in glioblastoma in vitro and in vivo to determine whether this could be used to predict the sensitivity of glioblastoma to gefitinib treatment." (PMID 27408849, 2013). "The EGFR gene is mutated or amplified in 45% of glioblastomas." (PMID 22348397, 2012). "For example, Murat and colleagues (2008) provided the first clinical evidence for the implication of high epidermal growth factor receptor (EGFR) expression associated with resistance to concomitant chemoradiotherapy in a “glioblastoma stem cell" or "self-renewal" phenotype." (PMID 22995409, 2012). "The loss of PTEN, which can be seen in 36 % of glioblastoma, may promote cellular resistance to EGFR kinase inhibitor therapy by dissociating EGFR inhibition from downstream PI3K pathway inhibition." (PMID 22918789, 2012). "Certain genotypes of the EGFR gene may be related to increased glioblastoma risk, indicating that germ line EGFR polymorphisms may have implications in carcinogenesis." (PMID 22662167, 2012). "Since EGFR gene amplifications were observed commonly in glioblastoma multiform, we hypothesized that certain mutations or haplotypes rendered the receptor susceptible to EGFR amplification." (PMID 22662167, 2012). "Since EGFR is amplified and/or mutated in 45% of all glioblastoma tumors, we also examined whether RhoG mediates EGF-stimulated signaling in glioblastoma cells." (PMID 22966858, 2012). "Furthermore, YKL-40 expression is inversely associated with epidermal growth factor receptor (EGFR) in glioblastoma, with loss of chromosome 10q and tends to be higher in astrocytomas with 10q23 loss of heterozygosity (LOH)." (PMID 24281168, 2010). "Overexpression of the gene encoding the epidermal growth factor receptor (EGFR) occurs commonly in glioblastoma, leading to activation of downstream kinases including phosphatidylinositol 3'-kinase (PI3K) and signal transducer and activator of transcription 3 (STAT3)." (PMID 20113523, 2010). "Two of these (PDGFRB and EGFR) are implicated in glioblastoma." (PMID 20964819, 2010). "In addition to serving a normal physiological function, aberrant expression of EGFR has also been linked with a number of pre-malignant or malignant diseases, including benign hyperplasia of the skin, mammary carcinoma, glioblastoma, and hepatic carcinoma." (PMID 11953893, 2002). "A mouse monoclonal antibody (IgG2b), 3C10, was produced against the truncated epidermal growth factor receptor (EGFR), encoded by the (type III) in-frame deletion mutation of 801 nucleotides of EGFR affecting the external domain, known to be expressed in some human glioblastoma." (PMID 8645581, 1996). "EGFR amplification frequently happens within extrachromosome DNAs (ecDNAs) and is a major mutation in glioblastoma (GBM)." (PMID 40678238, 2025).
glioblastoma (continued). "This study demonstrates that both [18F]FB-Gol1and [18F]FB-GR20 radiopharmaceuticals bind to the rat 101.8 glioblastoma and may serve as promising candidates for the development of a diagnostic radiotracers for selective diagnosis of EGFR expression in glial tumors." (PMID 41473440, 2025). "The observed specific activity of Pin-EGFR-armed eNK cells on multiple patient-derived GBM cells suggests that this product may be a new therapeutic option for patients with glioblastoma expressing EGFR or the EGFRvIII variant or diagnosed with an amplification of wild-type EGFR." (PMID 39996727, 2025). "The specific CAR construct employed in this protocol incorporates the 139 scFv,2,3 targeting the Egfrviii—a glioblastoma (GBM)-associated variant of the epidermal growth factor receptor (EGFR)." (PMID 38367235, 2024). "Amplifications and/or mutations of epidermal growth factor receptor (EGFR) occur in 57% of glioblastoma (GBM) patients." (PMID 39682716, 2024). "In addition to targeting wild-type EGFR, there has been significant progress in developing peptides that are specific to EGFR mutations, such as EGFRvIII, which is commonly associated with aggressive cancers like glioblastoma." (PMID 39126121, 2024). "In glioblastoma, EGFR aberration is a major genetic abnormality, and high EGFR expression is associated with angiogenesis and invasion; nonetheless, patients with high EGFR expression do not always have a significantly worse prognosis than those with low EGFR expression." (PMID 39117611, 2024). "The 2021 World Health Organization Classification of Central Nervous System Tumors updates glioma subtyping and grading system, and incorporates EGFR amplification (Amp) as one of diagnostic markers for glioblastoma (GBM)." (PMID 38595969, 2024). "Therefore, we hypothesized that EGFR alteration could prognosticate VTE risk in glioblastoma patients on the basis of some findings in NSCLC." (PMID 37232831, 2023). "EGFR pathway overexpression may be a common mechanism underlying glioblastoma recurrence." (PMID 36765632, 2023). "Moreover, glioblastoma patients with EGFR mutations or amplifications may have increased mTOR pathway activation, making mTOR inhibitors more effective in blocking downstream signaling." (PMID 37834408, 2023). "It is a matter of debate whether EGFR mutation in the primary tumor may be a marker for the disease course, prognosis, and diagnostic imaging of BMs, comparable to that described for primary brain tumors, such as glioblastoma (GB)." (PMID 37240478, 2023). "Glioblastoma multiforme (GBM) is the most malignant glioma, with a 30–60% epidermal growth factor receptor (EGFR) mutation." (PMID 35884836, 2022). "TC45, a 45-kDa variant of PTPN2, has the potential to dephosphorylate Delta EGFR, which is the most common mutation of the EGFR gene and promotes glioblastoma multiforme (GBM) growth." (PMID 36077422, 2022). "Several clinical trials have explored a combination of erlotinib with other agents to treat glioblastoma since it is believed that erlotinib would benefit patients with GBM with EGFR mutations or expression." (PMID 36199696, 2022). "Interestingly, EGFR-MAPK and PI3K-AKT-mTOR signaling is hyperactivated in glioblastoma by EGFR amplification, mutation of the MAPK pathway inhibitor Neurofibromin 1 and loss of the phosphatase and tensin homolog (PTEN) and is associated with resistance to radiation therapy in glioblastoma." (PMID 34771501, 2021). "Glioblastoma (GBM), a highly lethal primary brain tumor, expresses epidermal growth factor (EGFR), which is implicated in tumor proliferation and migration." (PMID 33959279, 2021). "Glioblastoma multiforme (GBM) is the most common and malignant brain tumor, and almost half of the patients carrying EGFR-driven tumor with PTEN deficiency are resistant to EGFR-targeted therapy." (PMID 34925034, 2021).